RN7SL655P (RNA, 7SL, cytoplasmic 655, pseudogene)
Gene: Miscellaneous RNA gene on chromosome 5 (154,349,428 to 154,349,725, forward strand). Ensembl gene ENSG00000241963.
Homologues: Orthologues: chimpanzee Metazoa_SRP (98% identical), macaque Metazoa_SRP (90% identical). Paralogues in human: RN7SL1 (86% identical), RN7SL2 (86% identical), RN7SL3 (85% identical), RN7SL711P (84% identical), RN7SL478P (83% identical), RN7SL709P (83% identical), RN7SL296P (83% identical), RN7SL398P (83% identical), RN7SL556P (82% identical), RN7SL220P (82% identical), RN7SL230P (82% identical), RN7SL516P (82% identical), and 708 more.